Y_RNA (Y RNA )
Gene: Miscellaneous RNA gene on chromosome 8 (13,160,178 to 13,160,279, forward strand). Ensembl gene ENSG00000200630.
Homologues: Orthologues: macaque Y_RNA (94% identical), pig Y_RNA (75% identical). Paralogues in human: Y_RNA (90% identical), RNY3 (89% identical), Y_RNA (89% identical), Y_RNA (88% identical), Y_RNA (87% identical), RNY3P1 (86% identical), Y_RNA (86% identical), Y_RNA (85% identical), RNY3P13 (84% identical), RNY3P14 (84% identical), RNY3P16 (84% identical), RNY3P5 (84% identical), and 96 more.